APOB (apolipoprotein B)
Diseases named in the same sentence as APOB in open-access papers (continued):
Sharing a sentence is not in itself a finding about the gene and the disease.
Arterial stenosis (3 papers, 2023 to 2024). Narrowing or constriction of the inner surface (lumen) of an artery. "Fibrinogen, apolipoprotein B/A, and neutrophils are identified as independent risk factors for arterial stenosis in female NSTE-ACS patients, while LVEF and high-density lipoprotein are protective factors." (PMID 39877025, 2024). "Our study shows the differential distribution of apoA-I and apoB IS subtypes and reveals the significance of the apoB/apoA-I ratio in assessing IS subtypes and arterial stenosis severity." (PMID 38978811, 2024). "In female NSTE-ACS patients, fibrinogen, apolipoprotein B/A, and neutrophils were independent risk factors for arterial stenosis, and LVEF and HDL-C were protective factors for arterial stenosis." (PMID 39877025, 2024). "Furthermore, we have revealed significant differences in apoB/apoA-I ratio across different degrees of arterial stenosis severity." (PMID 38978811, 2024).
atopic asthma (3 papers, 2022 to 2025). An asthma that is characterized by symptoms that are triggered by an allergic reaction caused by inhaled allergens such as dust mite allergen, pet dander, pollen and mold. "In atopic asthma, serum ApoA-I is positively associated with forced expiratory volume in 1 s (FEV1), which was used to assess airflow obstruction, whereas ApoB is correlated with more serious airflow obstruction." (PMID 36119695, 2022).
autism (3 papers, 2021 to 2022). Persistent deficits in social interaction and communication and interaction as well as a markedly restricted repertoire of activity and interest as well as repetitive patterns of behavior. "Initially, the serum protein profile of children with autism revealed different expression of apolipoprotein B 100 (ApoB100), complement factor H related protein 1 (FHR1), fibronectin 1 (FN1), and C1q." (PMID 35204837, 2022).
brain tumors (3 papers, 2010 to 2024). "What’s more, we have discovered daytime nap reasons apolipoprotein B and apolipoprotein causes the brain tumor." (PMID 39043735, 2024). "In mediation effect analysis, we proved apolipoprotein B completely mediates between daytime nap and brain tumor." (PMID 39043735, 2024).
breast tumors (3 papers, 2018 to 2025). "The activity level for the apolipoprotein B mRNA editing catalytic polypeptide-like–related signature SBS2 was significantly lower in breast tumors in the OM cohort." (PMID 40778578, 2025). "Apolipoprotein B mRNA editing enzyme catalytic polypeptide-like 3B (APOBEC3B) is a gene editing enzyme with cytidine deaminase activity and high expression of its mRNA in breast tumors have been shown to be associated with progressive cases and poor prognosis." (PMID 30093965, 2018).
cholestasis (3 papers, 2020 to 2025). Impairment of the bile flow caused by obstruction within the liver, or outside the liver in the bile duct system. "In the setting of cholestasis in which LDL-C appears to be severely elevated, further assessment for the presence of Lp-X may be performed through lipoprotein electrophoresis or measurement of apoB levels." (PMID 40465020, 2025).
chronic hepatitis C (3 papers, 2009 to 2014). "Total cholesterol, LDL cholesterol, and ApoB concentrations are significantly higher in chronic hepatitis C patients carrying a second IL28B major allele (CC in rs 12979860) compared with those possessing minor alleles (CT or TT)." (PMID 23193392, 2012). "In fact, serum levels of apolipoprotein B (ApoB) and cholesterol are reduced in chronic hepatitis C patients, suggesting that HCV may interfere with very-low density lipoprotein (VLDL) assembly and/or secretion." (PMID 21994542, 2009).
encephalitis (3 papers, 2010 to 2023). An acute inflammatory process affecting the brain parenchyma. "We explored the association between ApoB/ApoA-I ratio and anti-NMDAR encephalitis in the present study." (PMID 36119695, 2022). "Baseline characteristics of high and low ApoB/ApoA-I ratio in patients with anti-NMDAR encephalitis." (PMID 36119695, 2022). "Correlation analysis of factors related to ApoB/ApoA-I ratio in patients with anti-NMDAR encephalitis." (PMID 36119695, 2022). "Finally, due to the limitation of the sample size, patients with anti-NMDAR encephalitis are only divided into high and low ApoB/ApoA-I groups for subgroup analysis." (PMID 36119695, 2022). "Compared with the HCs, Hcy (p = 0.002), ApoB (p = 0.004), Lpa (p = 0.045), and ApoB/ApoA-1(p = 0.001) were significantly increased in patients with anti-NMDAR encephalitis." (PMID 37122291, 2023). "At the baseline, there were statistical differences in ApoA-1, ApoB, ApoB/ApoA-1, LPa, and Hcy between the anti-NMDAR encephalitis patients and the HCs." (PMID 37122291, 2023). "The ApoB/ApoA-I ratio in baseline and follow-up of patients with anti-NMDAR encephalitis were analyzed and compared with those in the healthy controls." (PMID 36119695, 2022). "The purpose of the present study is to clarify the relationship between the apolipoprotein B100/apolipoprotein A-I (ApoB/ApoA-I) ratio and anti-N-methyl-D-aspartate receptor (anti-NMDAR) encephalitis." (PMID 36119695, 2022). "Our study found that the serum ApoA concentration decreased, and the level of serum ApoB had no change, but the ApoB/ApoA-I ratio promoted the potential as an indicator of acute disease in patients with anti-NMDAR encephalitis." (PMID 36119695, 2022).
familial chylomicronemia syndrome (3 papers, 2015 to 2026). A rare autosomal recessive disease characterized by the buildup in the blood of fat particles called chylomicrons (chylomicronemia), severe hypertriglyceridemia, and the risk of recurrent and potentially fatal pancreatitis and other complications. "Recently data suggest that in subjects at high risk of FCS a triglyceride/total cholesterol ratio or triglyceride/apolipoprotein B ratio are feasible to initially screen for type I hyperlipoproteinemia." (PMID 36748937, 2023).
familial hypertriglyceridemia (3 papers, 2017 to 2022). "Between July 2018 and May 2021, 90 patients with HTG, including 83 patients with type IV hyperlipoproteinemia (HLP4) and 7 patients with HLP5, were identified by plasma apolipoprotein B (apoB) and lipoprotein electrophoresis." (PMID 36675730, 2022).
familial hypobetalipoproteinemia 1 (3 papers, 2020 to 2026). "In this regard, an interesting model is represented by patients affected by familial hypobetalipoproteinemia type 1 (FHBL1) who manifest a low LDL‐C status as a consequence of the presence of inactivating variants in the APOB gene." (PMID 41549954, 2026). "APOB (Apolipoprotein B) is a protein coding gene and associated disorder were familial hypobetalipoproteinemia 1 and 2 associated with activated Toll-like receptor (TLR) 4 signaling and lipoprotein metabolism pathway." (PMID 33339179, 2020). "Gain-of-function gene variants of PCSK9 occur with familial combined hypercholesterolemia, in which individuals have increases in plasma total cholesterol, ApoB, and/or triglyceride levels, while loss-of-function variants occur with familial hypobetalipoproteinemia-1." (PMID 34504056, 2021).
hypolipoproteinemia (3 papers, 2016 to 2022). Conditions with abnormally low levels of lipoproteins in the blood. "In addition, decreased ApoA1 (mainly seen in HDL) and ApoB (mainly seen in VLDL and LDL) can be explained by the hypolipoproteinemia, related to decreased cholesterol and inflammatory stress in SCD(Yalcinkaya, Unal, Oztas 2019)." (PMID 36459297, 2022).
Infertility (3 papers, 2018 to 2025). "The study identified a significant association between the AA (P value = 0.001) genotype and A allele (P value = 0.003) of the APOB rs13306194 variant and infertility in obese men." (PMID 38730451, 2024). "The present study observes a notable association between the AA genotype and A allele of the rs13306194 APOB gene, and the elevated risk of infertility in men who are obese." (PMID 38730451, 2024). "Our study’s novelty lies in examining azoospermic patients with APOB variants, highlighting NOA as a common form of infertility and allowing for a deeper exploration of APOB’s impact on spermatogenesis and related genetic influences." (PMID 38730451, 2024). "Moreover, the AA genotype of rs13306194 APOB was associated with a significant decrease in APOB gene expression in obese infertile men (p = 0.05)." (PMID 38730451, 2024). "Furthermore, the AA genotype of rs13306194 APOB was significantly associated with reduced APOB gene expression in obese infertile men (p = 0.05), suggesting a potential role for this genotype in the pathogenesis of male infertility." (PMID 38730451, 2024). "Notably, the AA genotype of rs13306194 APOB was associated with a significant decrease in APOB gene expression in obese infertile men." (PMID 38730451, 2024). "APOB expression levels were significantly lower in obese infertile men compared to obese fertile controls (p < 0.01)." (PMID 38730451, 2024). "APOB mRNA expression levels in testicular biopsy samples were determined using qPCR, and the results indicated significantly lower expression in the infertile group compared to the fertile group (p < 0.01)." (PMID 38730451, 2024). "APOB expression levels were markedly lower in obese infertile men compared to fertile controls (p < 0.05)." (PMID 38730451, 2024). "In addition to the observed differences in APOB expression, left and right testicular volume were found to have a lower mean value in the infertile obese infertile group compared to the fertile obese group." (PMID 38730451, 2024). "The apoB gene has been found to be expressed in the testes and epididymis of mice, and research has demonstrated that the expression of human APOB in these tissues can contribute to the correction of infertility issues in mice with a compromised Apob gene." (PMID 38730451, 2024). "Similarly, the APOB gene is located on chromosome 2p24.1, and the APOB gene signal peptide deletion polymorphism was reported not to be associated with infertility in Indian men." (PMID 29219278, 2018). "Also, menstrual blood serum was characterized as a less invasive source of infertility biomarkers, where EMILIN1, TRIP6, LAMB1, LAMC1, NID1, APOB, APOA4 were detected as the main differences in uIF patients as compared to healthy controls." (PMID 40861859, 2025).
ischemic disease (3 papers, 2014 to 2024). Lack of blood supply to an area of the body, resulting in impairment of tissue oxygenation. "In this study, we found from a genetic perspective that an increase in the ApoB/ApoA1 ratio is significantly associated with the occurrence of ischemic diseases, especially IHD, ischemic cerebrovascular disease, and PAD." (PMID 38310324, 2024). "In fact, the importance of APOB levels has been stressed because the Copenhagen City Heart Study showed that apolipoprotein B levels are associated with ischemic diseases." (PMID 36555767, 2022). "Data from the long-term intervention with pravastatin in ischemic disease (LIPID) trial and the MRC/BHF heart protection study showed that reduction of either LDL-C or apoB was associated with a reduction of coronary events, but they did not do the analyses on fatal and nonfatal events separately." (PMID 24982904, 2014).
large artery stroke (3 papers, 2021 to 2023). Stroke caused by the blockage of blood flow in one of the large arteries feeding the brain. "The inverse variance weighted Mendelian randomization (IVW-MR) revealed the low-density lipoprotein cholesterol (LDL-C) (OR, 1.46; 95% CI, 1.17–1.83; p = 0.0008) and apolipoprotein B (apoB) (OR, 1.46; 95% CI, 1.21–1.77; p = 0.0001) was positively correlated with large artery stroke (LAS)." (PMID 37528862, 2023).
lipodystrophy (3 papers, 2018 to 2024). A congenital or acquired disorder characterized by abnormal loss or redistribution of the adipose tissue in the body. "Second, apolipoprotein B (ApoB), the principal protein component of triglyceride and cholesterol-rich plasma lipoproteins, was identified to be a lipogenic factor connecting the altered metabolism and pathogenesis of PI-associated lipodystrophy." (PMID 37175645, 2023). "In addition, the inhibition of proteasomal apolipoprotein B (apoB) degradation and increased ER stress have been observed in cultures of hepatocytes and rat hepatocytes, respectively, resulting in increased VLDL and lipodystrophy." (PMID 38672720, 2024).
liver dysfunction (3 papers, 2020 to 2025). "Other blood parameters and markers of liver dysfunction such as aspartate aminotransferase, alanine aminotransferase, apolipoprotein B and lecithin cholesterol acyltransferase (LCAT) were not impacted." (PMID 33019707, 2020).
Lynch syndrome (3 papers, 2021 to 2023). An autosomal dominant hereditary neoplastic syndrome characterized by the development of colorectal carcinoma and a high risk of developing endometrial carcinoma, gastric carcinoma, ovarian carcinoma, renal pelvis carcinoma, and small intestinal carcinoma.
pneumonia (3 papers, 2017 to 2025). An acute, acute and chronic, or chronic inflammation focally or diffusely affecting the lung parenchyma, caused by an infection in one or both of the lungs (by bacteria, viruses, fungi, or mycoplasma.). "By analyzing various transcriptomic data repositories, we found strong supportive evidence for the role of MEIS1, TSPAN15 and APOBR (encoding the receptor of the APOB protein) in pneumonia in mouse and human models." (PMID 29751582, 2018). "The direct molecular link existing between APOB and APOBR is very suggestive of an association of pneumonia caused by S. pneumoniae and the APOB pathway." (PMID 29751582, 2018). "There were significant differences in total protein, globulin, FIB, APTT, TT, HDL-C, apolipoprotein A1 (APOA1), apolipoprotein B (APOB), and lipoprotein between patients with TB and those with pneumonia (P < 0.05)." (PMID 28278182, 2017).
Tangier disease (3 papers, 2017 to 2023). "Here, we show that total plasma sphingolipids were greatly reduced in patients with Tangier disease and apoB-lipoprotein free plasma of individuals with compound heterozygous ABCA1 mutations." (PMID 37601634, 2023).
Xanthelasma (3 papers, 2009 to 2025). The presence of xanthomata in the skin of the eyelid. "In individuals with xanthelasma, the APOB D allele was associated with less chance of having increased LDL-cholesterol (O.R. = 0.16, CI95% = 0.03-0.94, p = 0.042)." (PMID 21637672, 2009). "However, distinct APOB polymorphisms are highlighted as risk factors for alterations of the lipid profile in individuals with xanthelasma (APOB D) and controls (APOB X+)." (PMID 21637672, 2009). "In contrast, APOB mutation carriers showed lower median LDL-C and no xanthelasma, consistent with the known milder effect of APOB variants on LDL metabolism." (PMID 41398288, 2025). "On the other hand, APOB D allele was associated with less chance of an increase in LDL-cholesterol (≥ 130 mg/dL) (O.R. = 0.16, CI95% = 0.03-0.94, p = 0.042) in individuals with xanthelasma (data not shown)." (PMID 21637672, 2009).
amyloid (2 papers, 2021 to 2023). "Herein, we also show in transgenic amyloid mice remarkable colocation of apolipoprotein B (a marker of nascent hepatic and intestinal lipoproteins) with amyloid plaque and the accumulation of neutral lipids." (PMID 36875491, 2023).
Anderson's Disease (2 papers, 2011). "Anderson's Disease (AD)/Chylomicron Retention Disease (CMRD) is a rare hereditary hypocholesterolemic disorder characterized by a malabsorption syndrome with steatorrhea, failure to thrive and the absence of chylomicrons and apolipoprotein B48 post-prandially." (PMID 22104167, 2011).
aortic aneurysm (2 papers, 2024 to 2026). A ruptured aneurysm located in the wall of the proximal portion of the descending aorta proceeding from the arch of the aorta. "In terms of aortic aneurysm, there was a significant positive association between the ApoB/ApoA1 ratio and the incidence rates of aortic aneurysm, especially AAA (all PFDR<0.05)." (PMID 38310324, 2024). "Our research has found that an increase in the ApoB/ApoA1 ratio was significantly related to the formation of aortic aneurysm." (PMID 38310324, 2024). "In addition, an elevated ApoB/ApoA1 ratio also increased the incidence of aortic aneurysm (especially AAA), non-rheumatic valve diseases, and atrial flutter and fibrillation." (PMID 38310324, 2024).
aortic valve calcification (2 papers, 2024 to 2025). "A high APOB/APOA1 suggests that the balance between “promotion” and “inhibition” is disrupted, which may explain the increased risk of aortic valve calcification with an elevated APOB/APOA1." (PMID 40787622, 2025).
Atrophy (2 papers, 2013 to 2016). Any weakening or degeneration, especially through lack of use. "Additionally, OPVHs patients had GM atrophy in the left precentral gyrus and left insula cortex, and such atrophy is associated with a reduction in low-density lipoprotein cholesterol (LDL-C) and apolipoprotein-B (Apo-B)." (PMID 27656141, 2016).
autoimmune disease (2 papers, 2021). A disorder resulting from loss of function or tissue destruction of an organ or multiple organs, arising from humoral or cellular immune responses of the individual to their own tissue constituents. "Eleven proteins (increased: ATP5B, CALML5, COLEC11, FCGBP, PLEK, PLXND1; decreased: APOB, ATP8B1, FAM20C, LOXL3, TIMD4) were significantly altered in bvFTD with autoimmune disease compared to those without autoimmune disease." (PMID 34539672, 2021).
autoimmune thyroiditis (2 papers, 2023). "In women with PCOS, serum TSH levels appeared to be strongly correlated with higher LDL cholesterol concentrations, TG, apolipoprotein B (apoB), and free testosterone, but was negatively associated with apolipoprotein A (apoA), independent of age, BMI, or thyroid autoimmunity." (PMID 37635968, 2023).
calcification (2 papers, 2019 to 2022). Process by which organic tissue becomes hardened by the physiologic deposit of calcium salts. "For example, in the multicenter cohort study of young adults, high apoB and low LDL-C discordance demonstrate a 55% higher risk of midlife coronary calcification than the concordance group." (PMID 35665267, 2022).
carcinoma of the uterine cervix (2 papers, 2024 to 2025). "These authors also propose that, since A3B (apolipoprotein B mRNA editing enzyme) could impair genome stability, 5-hmC loss might increase the chances of accumulating mutations and of progressing from CIN3 to cervical cancer." (PMID 38635731, 2024).
cardiac hypertrophy (2 papers, 2018 to 2025). "The findings of this pilot study have shown early impaired TG and apoB-lipoprotein metabolism in overweight-obese women with and without PCOS, and this was associated with increased cIMT, and left ventricular diastolic dysfunction and hypertrophy." (PMID 40995592, 2025). "In terms of gene expression, transgenic expression of APOB in heart reduces lipotoxic cardiomyopathy in mice, but overexpression of FABP4 in cardiomyocytes aggravates cardiac hypertrophy in mice under pressure overload through activation of extracellular signal-regulated kinase (ERK) signaling." (PMID 30517173, 2018).